SH3BP1 (SH3 domain binding protein 1)
Description:
GTPase activating protein (GAP) which specifically converts GTP-bound Rho-type GTPases including RAC1 and CDC42 in their inactive GDP-bound form. By specifically inactivating RAC1 at the leading edge of migrating cells, it regulates the spatiotemporal organization of cell protrusions which is important for proper cell migration. Also negatively regulates CDC42 in the process of actin remodeling and the formation of epithelial cell junctions. Through its GAP activity toward RAC1 and/or CDC42 plays a specific role in phagocytosis of large particles. Specifically recruited by a PI3 kinase/PI3K-dependent mechanism to sites of large particles engagement, inactivates RAC1 and/or CDC42 allowing the reorganization of the underlying actin cytoskeleton required for engulfment. It also plays a role in angiogenesis and the process of repulsive guidance as part of a semaphorin-plexin signaling pathway. Following the binding of PLXND1 to extracellular SEMA3E it dissociates from PLXND1 and inactivates RAC1, inducing the intracellular reorganization of the actin cytoskeleton and the collapse of cells.
Synonyms: ARHGAP43
Tractability: Antibody: its Gene Ontology location is reachable by antibodies, with medium confidence. PROTAC: ubiquitination databases record sites on it; its protein half-life has been measured.
Gene: Protein-coding gene on chromosome 22 (37,634,654 to 37,656,117, forward strand). Ensembl gene ENSG00000100092.
Subcellular location: Cell projection; Cell junction, tight junction; Cell junction, adherens junction; Cell projection, phagocytic cup; Nucleus; Cytoplasm, cytosol
Subcellular location (Human Protein Atlas): Cytosol
Pathways (Reactome):
Signal Transduction: RAC1 GTPase cycle
Gene Ontology:
Molecular function: GTPase activator activity; protein binding; semaphorin receptor binding
Biological process: actin filament organization; cell junction assembly; cell migration; establishment of epithelial cell apical/basal polarity; negative regulation of small GTPase mediated signal transduction; phagocytosis, engulfment; positive regulation of GTPase activity; regulation of actin cytoskeleton organization; regulation of actin filament depolymerization; regulation of blood vessel endothelial cell migration; semaphorin-plexin signaling pathway; regulation of Rac protein signal transduction; regulation of small GTPase mediated signal transduction; signal transduction
Cellular component: adherens junction; bicellular tight junction; cell leading edge; cytosol; exocyst; lamellipodium; nucleus; phagocytic cup; plasma membrane; cytoplasm
Genetic constraint (gnomAD): Loss-of-function variants: 41 observed, 58.92 expected, observed/expected ratio (o/e) 0.7, 90% interval 0.54 to 0.9. The upper end of that interval is the gene's LOEUF score, 0.9, which puts it in group 3 of 6, group 1 being the genes least tolerant of losing a copy. Missense variants: 762 observed, 761.71 expected, observed/expected ratio (o/e) 1, 90% interval 0.94 to 1.06. Synonymous variants: 351 observed, 312.99 expected, observed/expected ratio (o/e) 1.12, 90% interval 1.03 to 1.23.
Homologues: Orthologues: chimpanzee SH3BP1 (99% identical), macaque SH3BP1 (98% identical), pig SH3BP1 (86% identical), dog SH3BP1 (86% identical), guinea pig SH3BP1 (84% identical), mouse Sh3bp1 (83% identical), rat Sh3bp1 (80% identical), rabbit SH3BP1 (68% identical), tropical clawed frog sh3bp1 (45% identical), zebrafish sh3bp1 (39% identical), Drosophila melanogaster RhoGAP92B (25% identical), Caenorhabditis elegans rga-8 (21% identical). Paralogues in human: ARHGAP17 (42% identical), ARHGAP44 (41% identical).
Diseases named in the same sentence as SH3BP1 in open-access papers:
SH3BP1 is named in the same sentence as 27 diseases in open-access papers, as found by Europe PMC text mining. Sharing a sentence is not in itself a finding about the gene and the disease. The quoted sentences say what the papers report.
cervical cancer (4 papers, 2020 to 2025). A primary or metastatic malignant neoplasm involving the cervix. "Wang and others found that SH3BP1 promotes the proliferation, migration, and chemoresistance of cervical cancer by affecting its downstream signaling pathway Rac-Wave2." (PMID 40688112, 2025). "For example, high expression of homologs of RGA-8, including SH3BP1 (also named Nadrin and ARHGAP17) is associated with more invasive and chemo-resistant cervical cancer, and liver cancer." (PMID 33243762, 2020). "Moreover, it has been shown that in the cisplatin-resistant cervical cancer tumors, expression of SH3BP1, Rac1 and WAVE2 mRNA is significantly upregulated compared to cisplatin-sensitive cancer tissues." (PMID 34572403, 2021). "Overexpression of SH3-domain-binding protein-1 (SH3BP1) promotes invasion, migration and chemoresistance of cervical cancer cells through increasing the activity of Rac1 and WAVE2." (PMID 34572403, 2021). "SH3BP1 belongs to the Rho GTPase activating protein family and mediates cell motility 72, in a similar manner to that observed during EMT in prostate cancer, hepatocellular carcinoma (HCC) and cervical cancer via the Rac family small GTPase 1-WASP family member 2 pathway 73-75." (PMID 35982909, 2022).
hepatocellular carcinoma (4 papers, 2016 to 2025). A malignant tumor that arises from hepatocytes. "Tumor invasion was also described as being promoted by an increased expression of Sh3bp1 and Vcam1 in hepatocellular carcinoma and gastric cancer, respectively." (PMID 36430209, 2022).
prostate carcinoma (3 papers, 2018 to 2022). A carcinoma that arises from epithelial cells of the prostate gland. "SH3BP1 is a direct target gene of TAZ in prostate cancer cells, mediating TAZ function in enhancing EMT-meditated cell migration." (PMID 30545369, 2018). "Moreover, the ETS factors ETV1/4/5 are necessary for TAZ transcription in prostate cancer cells, leading to the expression of SH3 domain-binding protein 1 (SH3BP1), which drives cell motility and constitutes a direct target of TAZ." (PMID 35954292, 2022).
chronic myeloid leukemia (2 papers, 2022 to 2025). "In leukemia, the Cobbl1/SH3BP1/PACSIN2 axis promotes drug resistance and progression of chronic myeloid leukemia by regulating Rac1 activity, while the expression level of SH3BP1 is inversely correlated with the prognosis of acute myeloid leukemia." (PMID 40688112, 2025).
Alzheimer disease (1 paper, 2019). A progressive, neurodegenerative disease characterized by loss of function and death of nerve cells in several areas of the brain leading to loss of cognitive function such as memory and language. "Recently, an mRNA transcript that is a partial fusion of SH3BP1 and CIN gene products has been linked to Alzheimer’s disease (AD)." (PMID 30934641, 2019).
breast carcinoma (1 paper, 2020). "In addition, FEME priming proteins SHIP2, FBP17, CIP4, Lamellipodin and SH3BP1 all promote tumor metastasis in several types of cancer, including lung and breast cancer." (PMID 32589750, 2020).
colorectal cancer (1 paper, 2025). A primary or metastatic malignant neoplasm that affects the colon or rectum. "We also explored the expression and function of the cancer susceptibility gene SH3BP1 in colorectal cancer." (PMID 40688112, 2025). "In addition, the susceptibility gene SH3BP1 found in this study has the role of promoting colorectal cancer, which has good research value and is expected to be a new target for colorectal cancer treatment." (PMID 40688112, 2025). "We then demonstrated differences in SH3BP1 expression between colorectal cancer and normal tissues using protein blotting and immunohistochemistry experiments." (PMID 40688112, 2025). "To further explore SH3BP1’s potential role in tumors, we downregulated the SH3BP1 gene in HCT116 and RKO colorectal cancer cells by transfecting them with si-NC and si-SH3BP1, respectively." (PMID 40688112, 2025). "Cell scratch and CCK8 experiments revealed that SH3BP1 knockdown slows tumor proliferation and migration, suggesting that SH3BP1 promotes proliferation and migration in colorectal cancer." (PMID 40688112, 2025). "A cell proliferation and migration assay verified that SH3BP1 has a role in promoting colorectal cancer." (PMID 40688112, 2025). "We used whole genome sequencing to capture information on gene targets that have mutations in the genomes of colorectal cancer and adjacent cancers and analyzed and screened high-frequency mutated genes (ATAD3B) and susceptibility genes (SH3BP1, C4orf54)." (PMID 40688112, 2025). "Based on previous studies, we hypothesized that SH3BP1 plays a tumor-promoting role in colorectal cancer." (PMID 40688112, 2025). "Additionally, the migratory effect of SH3BP1 on colorectal cancer cells was evaluated using a scratch wound healing assay." (PMID 40688112, 2025). "This suggests that SH3BP1 may promote tumor proliferation and migration in colorectal cancer and offers the opportunity to be used as a therapeutic target." (PMID 40688112, 2025). "Thus, SH3BP1 has the potential to be utilized as a therapeutic target for colorectal cancer and can provide new ideas for its treatment." (PMID 40688112, 2025). "Thus, SH3BP1 may promote tumor proliferation and migration in colorectal cancer and has the potential to be a new gene therapy target." (PMID 40688112, 2025). "Therefore, the experiment can further improve the validation of SH3BP1/Rac/Wave2 pathway, whether it can also play the role of promoting proliferation, migration, metastasis, and chemotherapy resistance in colorectal cancer." (PMID 40688112, 2025). "Notably, the function of SH3BP1 in colorectal cancer remains unknown." (PMID 40688112, 2025). "The proliferative capacity of the colorectal cancer cells (HCT116 and RKO) was significantly reduced in the SH3BP1 knockdown group (si-SH3BP1-1, si-SH3BP1-2) compared to the si-NC group, as demonstrated by a cell viability assay (CCK8)." (PMID 40688112, 2025). "Conversely, SH3BP1 expression was negligible in normal human intestinal epithelial cells (NCM460) but significantly increased in RKO and HCT116 colorectal cancer cells." (PMID 40688112, 2025). "However, the expression and related roles of SH3BP1 in colorectal cancer (CRC) have not been investigated." (PMID 40688112, 2025).
melanoma (1 paper, 2025). A malignant, usually aggressive tumor composed of atypical, neoplastic melanocytes. "For example, in melanoma, overexpression of SH3BP1 promotes the expression of Rac1 and Wave2, which promotes melanoma proliferation, invasion, and migration through the SH3BP1/Rac1/Wave2 pathway." (PMID 40688112, 2025).
Sleep apnea (1 paper, 2017). An intermittent cessation of airflow at the mouth and nose during sleep is known as sleep apnea. "Significant associations of symptoms of sleep apnea were observed with six rare variants [minor allele frequency (MAF) <1%] (located in ACE, AIFM3, LIPJ, MUC2, AP2A2, SH3BP1)." (PMID 29093733, 2017). "Of the six significantly associated variants, two could be tested for association with symptoms of sleep apnea in the FHS (located in MUC2 and SH3BP1)." (PMID 29093733, 2017).
cancer (5 papers, 2012 to 2025). A tumor composed of atypical neoplastic, often pleomorphic cells that invade other tissues. "The gene involved in this study, SH3BP1, has been found to be closely associated with various cancers in previous research reports." (PMID 40688112, 2025). "Take into account this, we roughly concluded that the more ideal cancer susceptibility genes are SH3BP1 and C4orf54." (PMID 40688112, 2025). "Finally, we performed pan-cancer expression analysis of SH3BP1, a susceptibility gene with a high mutation frequency." (PMID 40688112, 2025). "The probability of these six genes to be mutated in normal tissue adjacent to cancer is CPA6 (3.85%), ZNF888 (46.15%), SH3BP1 (76.92%), ANKRD16 (30.77%), ATN1 (11.54%), and C4orf54 (80.77%)." (PMID 40688112, 2025). "Our immunohistochemical analysis of pathological tissues from two patient groups revealed that SH3BP1 expression was consistently higher in cancer tissues than in normal tissues." (PMID 40688112, 2025). "Most samples were predominantly signature A. In this paper, we found that SH3BP1 gene expression increased in various cancers through pan-cancer analysis." (PMID 40688112, 2025). "Overexpression of SH3BP1 activates the invasion and migration of cancer cells by increasing the activity of Rac1‐WAVE2 signaling in cervical cancer and hepatocellular carcinoma." (PMID 35352878, 2022). "SH3 domain‐binding protein 1 (SH3BP1) is a RhoGTPase‐activating protein that is important for the process of cell motility and cancer invasion through the regulation of the Rac1 pathway." (PMID 35352878, 2022). "As the important roles of SH3BP1 and SH3BP1-Rac1 pathway in human cancer is emerging in recent studies." (PMID 26933917, 2016). "First, pan-cancer expression analysis revealed that SH3BP1 is highly expressed in many cancers." (PMID 40688112, 2025). "Consistent with our hypothesis, we first used pan-cancer species expression analysis and gene expression difference analysis in this study to verify differences in SH3BP1 expression between tumor and normal tissues in various cancers, including COAD and READ." (PMID 40688112, 2025). "Finally, experimental results showed that SH3BP1 was differentially expressed between colorectal tumors and normal tissues adjacent to cancer." (PMID 40688112, 2025). "In COAD and READ cancers, SH3BP1 expression was higher in tumor tissues than in normal tissues." (PMID 40688112, 2025). "To investigate whether SH3BP1 is differentially expressed in cancer and adjacent normal tissues, we performed protein blotting (WB) and immunohistochemistry (IHC) experiments." (PMID 40688112, 2025). "The RhoGTPase‐activating protein SH3BP1 activates Rac1‐WAVE2 signaling in diverse types of cancer." (PMID 35352878, 2022). "SH3BP1 has been shown to activate Rac1 to regulate cancer cell behavior." (PMID 35352878, 2022). "SH3BP1 promotes angiogenesis and then contributes on cancer development and metastasis." (PMID 26933917, 2016).
tumor (5 papers, 2016 to 2025). "High SH3BP1 expression in HCC tumors was found to be significantly associated with tumor VI and pathological HCC stage." (PMID 26933917, 2016). "The involvement of SH3BP1 in Rac1-WAVE2 signaling regulation is a question of interest to HCC aggressiveness research, and we hypothesize that SH3BP1 may be a novel tumor-associated SH3 domain gene in HCC." (PMID 26933917, 2016). "We also verified differential SH3BP1 expression in tumor and precancerous tissues using immunohistochemistry and protein blotting." (PMID 40688112, 2025). "The cell scratch assay showed that tumor cell migration was reduced in cells with low SH3BP1 expression." (PMID 40688112, 2025). "The CCK8 assay showed that tumor cell proliferation slowed down in cells with low SH3BP1 expression compared to cells with high SH3BP1 expression." (PMID 40688112, 2025). "Being an important angiogenic factor of HCC through Rac1-WAVE2 signaling, SH3BP1 promotes tumor invasion and microvessel formation contributing to HCC metastasis and recurrence." (PMID 26933917, 2016). "In conclusion, SH3BP1 induces Rac1-WAVE2 signaling to promote tumor vascular invasion and MVD formation related to HCC metastasis." (PMID 26933917, 2016). "In nude mice with HCCLM3 tumor transplantation, the lesion size in the Si-SH3BP1 group was significantly smaller than that in controls (1.12 ± 0.85 vs. 2.45 ± 0.97 cm3, P < 0.05)." (PMID 26933917, 2016). "Comparing the expression of SH3BP1, CPA6, ZNF888, and NKRD16 in COAD and READ tumor and normal tissues revealed that SH3BP1 expression increased in COAD and READ and was more prevalent in tumor tissues than in the other susceptibility genes obtained by whole-genome sequencing." (PMID 40688112, 2025). "The expression levels of SH3BP1, KDM5B (involved in serine/threonine kinase activity pathway) and PI4KA (belongs to inositol phosphate metabolism pathway) were notably increased in cells overexpressing CPTP, and are associated with tumor progression." (PMID 35982909, 2022). "SH3BP1 overexpressed in tumor is significantly correlated to poor prognosis of HCC." (PMID 26933917, 2016). "Moreover, a significant correlation was verified between SH3BP1 expression and MVD (R = 0.823, P < 0.01), revealing the significance of increased SH3BP1 expression in HCC tumor angiogenesis." (PMID 26933917, 2016).
SH3BP1 also shares sentences with these, for which no sentence is quoted: liver cancer (2 papers); acute myeloid leukemia (1); autoimmune (1); cervical squamous cell carcinoma (1); colon adenocarcinoma (1); gastric adenocarcinoma (1); gastric cancer (1); leukemia (1); liver cirrhosis (1); Lung Squamous Cell Carcinoma (1); pancreatic adenocarcinoma (1); rectal adenocarcinoma (1); Renal Clear Cell Carcinoma (1); testicular germ cell tumor (1); uterine sarcoma (1); viral infection (1).